JAK2 (Janus kinase 2)
Diseases named in the same sentence as JAK2 in open-access papers (continued):
Sharing a sentence is not in itself a finding about the gene and the disease.
viral infection (15 papers, 2014 to 2026). "JAK2 expression inhibitors are also useful in controlling inflammation caused by response to viral infection." (PMID 38500508, 2024). "Therefore, our research highlights the possibility that a highly JAK2-selective inhibitor would enhance the risk for a cutaneous viral infection." (PMID 37298195, 2023). "Collectively, these findings identify PB05 as a dual PB2/JAK2 inhibitor that effectively couples antiviral efficacy with immunomodulatory activity, promoting a therapeutic strategy for the treatment of severe influenza and other viral diseases associated with excessive inflammation." (PMID 41752472, 2026). "SARS-CoV-2 in human patients when treated with JAK2 inhibitors resulted in preventing severe respiratory side effects resulting from viral infection with minimal impact on the hosts immune system." (PMID 38500508, 2024). "Our results indicate in two different viral models (VV and HSV-1) that JAK2-selective inhibitors reduce IFNγ-mediated protection from viral infection in KC." (PMID 37298195, 2023). "IFNγ-mediated resistance to viral infection was reversed by JAK2 inhibition (366 ± 294% increase in infection)." (PMID 37298195, 2023). "This would further substantiate the importance of JAK2 signaling in the skin as a protective response to viral infection." (PMID 37298195, 2023). "Our study suggests that Jak2 and PAPR1 are expressed higher in vHCC than in non-viral infection-associated HCC (nvHCC) and the normal liver." (PMID 34199353, 2021). "In order to further understand the connection between the JAK2 expression and virus infection, we conducted follow-up IHC experiments of different liver samples." (PMID 34199353, 2021). "Activation of the JAK2/STAT3 pathway is associated with inflammation, and inflammation subsequent to viral infection is one factor that initiates and promotes the development of cancer." (PMID 26219895, 2016). "In addition, these compounds show no immediate risks of toxicity, including hepatic, neurotoxic, or mutagenic effects, reinforcing their potential as safe JAK2 inhibitors for viral infection treatment." (PMID 39598448, 2024). "Specifically, MOL004112 and MOL002235 do not show any hepatic, neurotoxic, immunotoxic, mutagenic, or cytotoxic effects, and they are unable to cross the blood–brain barrier (BBB), which is advantageous for developing JAK2 inhibitors for viral infection treatment." (PMID 39598448, 2024). "This suggests that JAK2 is important in the host response to viral infection, and that therapies which diminish this signaling pathway in the skin could enhance the likelihood of developing severe cutaneous viral infections." (PMID 37298195, 2023). "The JAK2 and IL6/JAK2/STAT3 signaling pathways are therapeutic targets for treating excessive inflammatory response to virus infection, where PIK3CB, the target of miRNA−34a participated in TCR−mediated NF−κB signaling after binding to B7 ligand on antigen presenting cells (APC)." (PMID 36298658, 2022). "The related downstream JAK1 and JAK2 in the IFNGR pathway induced by viral infection are related." (PMID 34199353, 2021). "As for DDX58, NFκB1, TOLLIP, RIPK1, DDX3Y, TRIM25 and JAK2, which are involved in antiviral signalling transduction, both increased mRNA abundance and switched poly(A) sites eventually led to enhanced protein production following viral infection." (PMID 28233779, 2017). "As a means to assess whether the JAK2/STAT3 signaling pathway may contribute to depressive‐ and anxiety‐like behaviors in miR‐204‐5p deficient rats, we injected SC99 or WP1066, the JAK2/STAT3 signaling pathway inhibitor, for 7 days after virus infection 2 weeks in miR‐204‐5p knockdown rats." (PMID 39792918, 2025). "DEGs unique to infected cells mapped to host defense (MYD88, C3, CASP4, JAK2, and OSM), viral infection (RNASE6 and SVVORFs), and protein synthesis (RPL18 and RPS16)." (PMID 38887303, 2024).
viral infection (continued). "The results showed that SKIV2L2, JAK2, PIK3CB, and MAPK8 were related to virus infection." (PMID 36298658, 2022). "In addition, STAT1 is a downstream gene of JAK2 in IFN-gamma signaling pathways, which can infer the significance of JAK2 in viral infection." (PMID 34199353, 2021).
esophageal squamous cell carcinoma (14 papers, 2012 to 2025). Esophageal squamous cell carcinoma (ESCC) is a type of esophageal carcinoma (EC) that can affect any part of the esophagus, but is usually located in the upper or middle third. "In summary, in this study, we demonstrate that fedratinib suppresses proliferation, migration, and apoptosis resistance in esophageal squamous cell carcinoma through inhibition of the JAK2/STAT3 signaling pathway." (PMID 41476794, 2025). "The 235aa polypeptide encoded by circ_8199 is mainly located in the cytoplasm, and can inhibit esophageal squamous-cell carcinoma cell proliferation by binding to and inhibiting the activity of OGT (O-linked N-acetylglucosamine transferase) through the JAK2 (Janus kinase 2)-STAT3 pathway." (PMID 40034125, 2025). "Notably, the effect of AZD1480 (a JAK2 inhibitor) on esophageal SCC cells was comparable to that of LicB." (PMID 39021879, 2024). "In addition, LicB inhibited esophageal SCC growth by directly inhibiting the activity of JAK2 and its subsequent signaling pathway." (PMID 39021879, 2024). "In mouse esophageal squamous cell carcinoma, CAFs-secreted Wnt family member (WNT2) has been linked to suppression of the DC-initiated antitumor T-cell response via the suppressor of cytokine signaling 3 (SOCS3)/phosphorylated Janus kinase 2 (p-JAK2)/phosphorylated STAT3 (p-STAT3) signaling pathway." (PMID 36338519, 2022). "Research suggests that the JAK2/STAT3 pathway is involved in B7-H4-mediated IL-6 secretion in esophageal squamous cell carcinoma (ESCC) cells and enhances the growth and tumorigenicity of cells." (PMID 35505420, 2022). "In esophageal squamous cell carcinoma (ESCC), CAF‐derived WNT2 inhibits DC differentiation through the SOCS3/p‐JAK2/p‐STAT3 signaling cascade, thereby suppressing immune responses." (PMID 41164803, 2025). "In esophageal squamous cell carcinoma, CAFs secrete WNT2 to inhibit the SOCS3/p‐JAK2/p‐STAT3 pathway, thereby suppressing CD8+ T‐cell activation." (PMID 41164803, 2025). "A previous study found that acylglycerol kinase overexpression augmented JAK2/STAT3 sustained activation, promoting tumorigenicity of esophageal squamous cell carcinoma (ESCC)." (PMID 38182570, 2024). "lncRNA Xist involves esophageal squamous cell carcinoma development via regulation of miR-101/EZH2 axis, and facilitates esophageal squamous cell carcinoma proliferation, apoptosis, migration, and invasion via regulation miR-494/CDK6 axis and activation of JAK2/STAT3 signal pathway." (PMID 34178980, 2021). "In esophageal squamous cell carcinoma (ESCC), AGK directly binds to the Janus kinase homology 2 (JH2) domain of JAK2 to block the inhibition of JAK2 mediated by JH2, which leads to the activation of the JAK2/STAT3 signaling pathway and enhances the tumorigenicity of ESCC cells in vivo and in vitro." (PMID 34368119, 2021). "The Janus Kinase 2/Signal Transducer and Activator of Transcription 3 (JAK2/STAT3) pathway plays an important role in the occurrence, development and metastasis of esophageal squamous cell carcinoma (ESCC) and is related to the development of resistance to ionizing radiation in ESCC." (PMID 33330321, 2020).
oral cancer (14 papers, 2018 to 2025). "Janus kinase 2 (JAK2) is a tyrosine kinase receptor that belongs to the JAK family kinases is linked to oral cancer." (PMID 34675459, 2020). "It has been shown that CCL4 stimulates VEGF-C expression by activating the JAK2/STAT3 signaling pathway, which is frequently linked with oral cancer cell proliferation, invasion, and angiogenesis." (PMID 32961854, 2020). "The JAK2/STAT3 signaling pathway is implicated in cell invasion and angiogenesis in oral cancer, as well as head and neck metastasis." (PMID 29599774, 2018). "This could be explained by the important role of CCL18 in oral cancer where it promotes hyperplasia and metastasis by JAK2/STAT3 signaling pathways." (PMID 34025655, 2021). "CCL4 stimulation of oral cancer cells augmented JAK2 and STAT3 phosphorylation." (PMID 29599774, 2018). "Besides, CCL18 could facilitate the proliferation of oral cancer cells through the JAK2/STAT3 signaling pathway." (PMID 36850011, 2023). "And in IFN-γ-stimulated human oral cancer cells, p-JAK1 and p-JAK2 are inhibited by EGCG, and EGCG inhibits STAT1 translocation to the nucleus." (PMID 34539403, 2021). "Although the blueberry supplement failed to alter cellular viability in SCC131 oral cancer cells, the purified malvidin component induced a marked growth reduction (IC50 of 62 μM) associated with reduced p-JAK2 and nuclear p-STAT3 levels." (PMID 36355554, 2022). "Moreover, phosphorylation of protein kinase C delta PKC-delta, Janus kinase 1 (JAK1), and Janus kinase 2 (JAK2), which are the upstream activators of STAT1 are also inhibited by EGCG in interferon gamma (IFNγ)-stimulated oral cancer cells." (PMID 32290543, 2020).
antiphospholipid syndrome (13 papers, 2018 to 2025). A disorder caused by the presence of autoantibodies directed against phospholipids, causing a hypercoaguable state, which may result in blood clots, stroke, heart attack, and in women, significant pregnancy-related complications, including miscarriage and still birth. "Chronic factors include hereditary (protein C or S deficiency, factor V Leiden, prothrombin G20210A mutation), and acquired thrombophilias (antiphospholipid antibody syndrome, Janus kinase 2 (JAK2) mutation, malignancy, inflammatory bowel disease, Behçet disease, etc.)." (PMID 39735097, 2024).
B-cell lymphoma (13 papers, 2015 to 2025). "JAK1_8709 targets JAK1/JAK2, studies have established an excellent efficacy on treating B‐cell lymphoma with anti‐JAK management." (PMID 39811936, 2025). "NFATc1 can also be activated by the B cell receptor (BCR) and upregulate the IL-10 chemokine to activate the JAK2/STAT3 pathway in B cell lymphoma cells, ultimately inducing PD-L1 expression." (PMID 37138354, 2023). "In the perspective of B-cell lymphoma we propose JAK2 to be inhibited by ibrutinib and regulating the subsequent phosphorylation of STAT3 and 6 leading to decreased transcription of M2 macrophage phenotype genes." (PMID 32824276, 2020). "In particular, JAK2 phosphorylation of EZH2 at tyrosine 641 is able to promote EZH2 degradation via the SCFβ-TrCP E3 ubiquitin ligase pathway in B cell lymphoma." (PMID 30159126, 2018). "Several clinical phase I/II studies, evaluating the safety and efficacy of JAK1 and JAK2 inhibitors in patients with relapsed/refractory B-cell lymphoma, including DLBCL are ongoing (NCT01905813, NCT01431209) or in planning." (PMID 26654227, 2015). "In addition, inhibition of JAK2 does not only block the activation of STAT3 but also the activity of STAT1 in B-cell lymphoma." (PMID 26654227, 2015). "As JAK1 and JAK2 modulate epigenetic regulation of gene transcription through tyrosine phosphorylation of the histone protein H3 in leukemic- and B cell lymphoma- cell lines, we performed in vitro kinase assays to address whether JAK3 was also able to phosphorylate Histone H3." (PMID 33466582, 2021). "Combination of ibrutinib and monoclonal antibody treatment in the context of B-cell lymphoma provides synergy independent of BTK-inhibition via targeting of JAK2." (PMID 32824276, 2020). "Furthermore, we argue that inhibition of JAK-STAT signaling might sensitize B-cell lymphoma cells towards macrophage mediated ADCP and JAK2 inhibitors should be evaluated and utilized in future treatment concepts of B-cell malignancies." (PMID 32824276, 2020).
erythroleukemia (13 papers, 2013 to 2024). Acute erythroid leukemia characterised by the presence of at least 50% erythroid precursors and at least 20% myeloblasts in the bone marrow. "Next, derivatives were tested against the HEL (human erythroleukemia) cell line since the mutation JH2 pseudokinase domain of the Janus kinase 2 gene (JAK2 V617F) existed in it." (PMID 35011562, 2022). "Interestingly, the Jak2 gene locus was among the most common CIS in this model furthermore underlining cooperation of ERG and constitutively active JAK2 in murine erythroleukemia." (PMID 33898929, 2021). "These beneficial effects can be explained by the BW18-mediated inactivation of PDGFRB and JAK2/STAT3 pathway in erythroleukemia cells." (PMID 38794198, 2024). "In conclusion, N2 shows great promise as a differentiation therapy for erythroleukemia, offering a novel approach by targeting JAK2-mediated signaling pathways to induce megakaryocytic differentiation." (PMID 39791711, 2024). "The HEL cell line, originating from a patient with erythroleukemia, exhibits accelerated growth in culture and displays reduced sensitivity to ruxolitinib, even when administered at doses capable of inhibiting JAK2/STAT activation." (PMID 39261151, 2024). "In addition, in human erythroleukemia (HEL) cells, which are homozygous for the V617F mutation in JAK2, high expression of c-Myc and ODC was observed, and treatment with AG490 diminished the phosphorylation of JAK2 and STAT5, and also the expression of c-Myc and ODC." (PMID 23300995, 2013). "In summary, N2 represents a potent differentiation therapy candidate for erythroleukemia, uniquely targeting JAK2 and activating downstream JAK2/STAT3, JAK2/PKCδ/STAT3 and JAK2/PKCδ/MAPK pathways to facilitate megakaryocytic differentiation." (PMID 39791711, 2024). "We designed 10 sgRNAs within a 200 bp window centered on JAK2 V617 and tested them by nucleofecting individual Cas9-sgRNA ribonucleoprotein (RNP) complexes into K562 human erythroleukemia cells." (PMID 33661998, 2021).
Budd-Chiari syndrome (12 papers, 2011 to 2025). "The liver recipient was a 30-yr-old female diagnosed with Budd-Chiari syndrome and with a pathogenic JAK2 V617F (c.G1849T) variant." (PMID 34301805, 2021). "Research has shown that 30–50% of patients with splanchnic-vein thromboses associated with Budd-Chiari syndrome (including portal-venous and hepatic-vein thrombosis) harbour a somatic mutation of the JAK2 gene (JAK2 V617F) that constitutively activates JAK2 kinase." (PMID 22395661, 2012). "In the prospective multicenter pilot study for rivaroxaban as a treatment for SVT, JAK2 p.V617F was detected in 13 of 50 patients tested (26%); patients with Budd-Chiari syndrome or liver cirrhosis were excluded." (PMID 38274463, 2023). "Budd-Chiari syndrome (disease gene: F5, JAK2) is Cardiovascular diseases." (PMID 33126852, 2020). "Our results do not support the routine screening of JAK2 V617F mutation in patients with splanchnic thrombosis in terminal cirrhosis or malignancy, except when patients have Budd-Chiari syndrome." (PMID 22909075, 2012). "Determination of JAK2 mutation is useful for investigating the aetiology of portal vein thrombosis or Budd Chiari syndrome, if the aetiology of thrombosis is not obvious." (PMID 21505581, 2011).
chronic myelomonocytic leukemia (12 papers, 2013 to 2025). A myelodysplastic/myeloproliferative neoplasm which is characterized by persistent monocytosis, absence of a Philadelphia chromosome and BCR/ABL fusion gene, fewer than 20 percent blasts in the bone marrow and blood, myelodysplasia, and absence of PDGFRA or PDGFRB rearrangement. "Here, a JAK2, an SRSF2, and an ASXL1 variant were detected in a patient with chronic myelomonocytic leukemia." (PMID 35884491, 2022). "Consistent with this, a recent report demonstrated that combined treatment with MEK and JAK2 inhibitors significantly prolonged survival in an N-RasG12D-induced CMML (chronic myelomonocytic leukemia) mouse model." (PMID 35352806, 2022). "Variants in TET2, JAK2, and SRSF2 occur in 10–60% of patients with sporadic chronic myelomonocytic leukemia." (PMID 35884491, 2022). "Ruxolitinib, the first JAKinib approved by the United States Food and Drug Administration (FDA), is a potent inhibitor of JAK1 and JAK2, used for primary myelofibrosis and its effects have been also studied in MDS, AML, ALL, chronic myelomonocytic leukemia (CMML) and chronic myeloid leukemia (CML)." (PMID 34055801, 2021).
Crohn disease (12 papers, 2013 to 2025). A gastrointestinal disorder characterized by chronic inflammation involving all layers of the intestinal wall, noncaseating granulomas affecting the intestinal wall and regional lymph nodes, and transmural fibrosis. "For the interaction pair MST1‐JAK2, the susceptibility to Crohn's disease was 4.34 higher for genotypes with allele G at rs144982232 in MST1 or with allele C at rs1159782 in JAK2 than those with allele A at rs144982232 and T at rs1159782 (odds ratio = 4.34)." (PMID 29441677, 2018). "Other evidence suggested a significant association between some SNPs included in the JAK2 haplotypeGGCC_46/1 (e.g., rs10758669) and inflammatory disorders such as ulcerative colitis and Crohn's disease." (PMID 29641446, 2018). "JAK2 rs1159782 (T>C) was also strongly associated with Crohn's disease (P = 2.34 × 10−4; odds ratio = 3.72)." (PMID 29441677, 2018). "Recently, JAK2 SNP rs10758669 was also reported to be associated with increasd susceptibility for Crohn’s disease (CD)." (PMID 23717640, 2013). "Recently, great advances were made in the understanding of the pathogenesis of the polymorphisms of JAK2 in patients with various diseases, including hematologic malignancies and Crohn's disease." (PMID 23717640, 2013). "Genome-wide association studies have revealed that IL23R and five additional genes involved in Th17 differentiation (IL12B, JAK2, STAT3, CCR6 and TNFSF15) are associated with susceptibility to Crohn’s disease." (PMID 36498596, 2022). "The large odds ratios indicated a strong risk effect in the MST1, JAK2 and NOD2 gene to Crohn's disease." (PMID 29441677, 2018). "For example, the Janus kinase 2 (JAK2) single nucleotide polymorphism (SNP) rs10758669, a SNP that tags the 46/1 haplotype associated with JAK2V617F-mutated MPN, was also identified previously to be associated with Crohn’s disease." (PMID 29614027, 2018). "Additionally, the mRNA and protein expression of JAK2 and IL-23R were increased in UC and Crohn's disease (CD) patients." (PMID 24382939, 2013). "The co‐involvement of NOD2, JAK2, MUC19 and MST1 in mucosal defence and inflammation in Crohn's disease therefore deserves further study." (PMID 29441677, 2018). "For main effects, JAK2, TNFSF15, ZNF365 and PTPN22 showed consistent small P‐values in the original sequencing data as well as the validation with IBD and Crohn's disease data sets." (PMID 29441677, 2018).
Down syndrome (12 papers, 2013 to 2024). "Children with Down syndrome have a 10–20-fold increased incidence of acute leukemia, and JAK2 mutations are found in 20% of DS-ALL." (PMID 33672930, 2021). "JAK1 mutations have mainly been observed in T-ALL and high-risk B-ALL while JAK2 mutations have been identified in Down syndrome and high-risk B-ALL." (PMID 29642462, 2018). "Overt JAK2 signaling is also associated with childhood leukemia in Down syndrome (DS) patients." (PMID 33672930, 2021). "For instance, Down syndrome, one of the leading causes of ID, is related to the presence of somatic mutations in GATA1 and JAK2, which are associated with acute megakaryoblastic leukemia and ALL." (PMID 34673770, 2021). "This could be explained by the reported low frequency of CRLF2 pathogenic variants in pediatric cohorts, which is approximately 2%, and the higher co-occurrence (about 10%) between JAK2 variants and CRLF2-r in non-Down Syndrome ALL." (PMID 38370004, 2024). "In the current study, we also observed co-occurrence of JAK2 and KRAS lesions in non-Down syndrome BCP-ALL cells." (PMID 29163799, 2017).